NOD2 (nucleotide binding oligomerization domain containing 2)
Diseases named in the same sentence as NOD2 in open-access papers (continued):
Sharing a sentence is not in itself a finding about the gene and the disease.
infection (continued). "To assess the impact of NOD2 on the integrity of gut barrier following infection, we challenged EDMs from WT, ELMO1 KO and NOD2 KO mice with AIEC-LF82 infection and then assessed the gut barrier integrity by measuring the transepithelial electrical resistance (TEER)." (PMID 36694274, 2023). "nod1 and nod2 play fundamental and pleiotropic roles in host defense against infection." (PMID 36991462, 2023). "Furthermore, NOD1 and NOD2 play a role in stimulating Th1 cell responses required for parasitic clearance in mouse models of infection with Toxoplasma gondii, Trypanosoma cruzi, and Leishmania infantum." (PMID 37006312, 2023). "An NTM model of infection could permit a more rapid and/or convenient investigation of NOD2 in this phenotype." (PMID 37262021, 2023). "Similar to ELMO1 deficient EDMs, NOD2 KO EDMs and ELMO1 KO EDMs treated with GSK717 also had a defect in bacterial internalization, and a delayed clearance of bacteria thus leading to higher load after 12 h of infection." (PMID 36694274, 2023). "To address this, we used Mincle-/-Nod2-/- (double knockout, DKO) mice previously generated (with the corresponding single knockouts, SKOs) to model genetic susceptibility to mycobacterial disease during infection with Mtb." (PMID 35418999, 2022). "Bacteria will activate NOD2 during infection and increase the expression level of NOD2." (PMID 35682909, 2022). "We speculate that NOD1 might have replaced the function of NOD2 and played a role in infection in poultry." (PMID 34745142, 2021). "Our recent study have identified 25HC-integrin-FAK-NFκB signaling network that triggers pro-inflammatory response during activation of cytosolic pattern recognition receptor (PRR) Nod2 and infection by respiratory viruses [respiratory syncytial virus (RSV) and influenza A virus (IAV)]." (PMID 34551004, 2021). "In other cell types than neutrophils NOD2 might contribute to immune stimulation, because in vivo NOD2 mice showed delayed clearance of A. phagocytophilum in the early phase of infection." (PMID 33747981, 2021). "However, when we immunized mice devoid of either Dectin-1 or Nod2 with gut-evolved C. albicans R24, most of them survived subsequent infection with virulent C. albicans." (PMID 34881192, 2021). "Therefore, it is likely that, in the early stage of infection, the attenuated type I IFN signal by the deficiency of NOD2 leads to the decrease in NO production and thus impairs the bacterial clearance." (PMID 34777348, 2021). "This regulation is essential for modulating the response to both NOD2 stimulation and infection with invasive intestinal pathogens, suggesting that it might play a critical role at the level of the intestinal mucosa." (PMID 33559391, 2021). "However in vivo, NOD2-/- mice had elevated bacterial loads in the early phase of infection compared to WT animals." (PMID 33747981, 2021). "Understanding the nuances of the roles NOD1 and NOD2 play in metabolism may be essential for effective therapies for these prevalent metabolic diseases, chronic inflammatory diseases, or infection." (PMID 33503814, 2021). "NOD1/NOD2 depletion affected bacterial clearance in early infection." (PMID 32487756, 2020). "C57BL/6 and NOD2-/- mice show similar parasitism during the acute and chronic phases of infection." (PMID 32986710, 2020). "Interestingly, during the chronic phase of the infection there was inflammation and hypertrophy of the longitudinal and circular muscular layer more pronounced in the colon and jejunum from NOD2-/- animals, when compared to wild type C57BL/6 mice." (PMID 32986710, 2020). "However, impaired expression of CD-associated genes ATG16L1 or IRGM in THP-1 macrophages and NOD2 in NOD2−/− murine peritoneal macrophages led to an increased AIEC intracellular replication and to the secretion of IL-6 and TNF-α upon AIEC LF82 infection." (PMID 32466328, 2020).
infection (continued). "NOD2 mutations are likely to involve ISC dysfunction characterized by a delay in epithelial restitution, followed by intestinal injury that includes not only infection but also medication, and chemical or physical stress." (PMID 31480799, 2019). "Indeed, our previous studies showed that NOD2 was required for E. faecium-mediated protection against enteric pathogen infection." (PMID 30969170, 2019). "In humans, polymorphism in TLRs (TLR1, NOD2, TLR6 and TLR10) might be associated with the reduced production of cytokines after infection and finally less responsiveness of macrophages to infection." (PMID 29321921, 2018). "However, low expression of NOD2 has also been reported in intestinal epithelial cells, where certain stimuli such as pro-inflammatory cytokines or infection with enteroinvasive pathogens can up-regulate its expression." (PMID 29616010, 2018). "Furthermore, our study also finds that the NOD2 expression is firstly increased 12 h after infection (early stage of Streptococcus pneumoniae meningitis) in the Streptococcus pneumoniae meningitis model, which is even higher at 24 h and 48 h." (PMID 30186539, 2018). "It is interesting that NOD2-deficient mice are susceptible to pathogen infection via the oral route but not intravenous or peritoneal routes." (PMID 30089512, 2018). "Based on our study, Nod2-deficient mice are more susceptible to A. baumannii at early, but not at late time points of infection." (PMID 29234083, 2017). "Furthermore, current literature evidences that NOD2 is also able to control viruses’ and parasites’ infections." (PMID 28253332, 2017). "Moreover, infection by RNA viruses, including RSV, NV, and HIV-1, is commonly associated with Nod2 upregulation, which results in the overproduction of TNF-α." (PMID 28253332, 2017). "Within 24 h following the latest infection viable C. jejuni could be detected in 60.0% of fecal samples derived from NOD2−/− mice with low median loads of approximately 102 CFU per g feces only." (PMID 28127403, 2017). "The exact mechanisms involved in NOD2-mediated Leishmania killing need to be further explored, although it is known that proinflammatory cytokines promote the induction of microbicidal molecules after infection with Leishmania spp.10,19–22,44." (PMID 29123157, 2017). "Since Rip2 is the best-studied interaction partner of Nod2, we evaluated whether this adaptor protein was involved in Nod2 triggered phenomena during the infection." (PMID 27377650, 2016). "After infection at multiplicity of 0.1 or 1 MDP induced NOD2 by 6.5- and 2.5-fold, respectively." (PMID 26830977, 2016). "Our data provide evidence that Nod2 activation led to a complementary production of proinflammatory cytokines, thus, consequently, minimizing the risks of a deleterious reactivation of the infection." (PMID 27377650, 2016). "In order to observe whether the expression pattern of this receptor was altered by the infection, we observed Nod2 protein expression pattern by microscopy." (PMID 27377650, 2016). "As such, we hypothesize that a failure in the innate immune recognition of M. ulcerans via NOD2 might divert the proper activation of immunological autophagy, therefore permitting progression of infection and development of more severe phenotypes." (PMID 27128681, 2016). "Although complementary studies should be undertaken to characterize the exact mechanism of action of Nod2 during the infection, the results presented here highlights this intracellular receptor as a potential target for therapy against the clinical manifestations of the disease." (PMID 27377650, 2016). "In a mouse model of M. tuberculosis infection NOD2 deficiency did not affect the early phase of infection and bacterial burden, but the pulmonary bacterial burden was increased and survival decreased in NOD2-deficient mice." (PMID 27297389, 2016).
infection (continued). "We found that Nod2−/− BMDMs presented a higher proportion of infected cells after 24 h of infection, in addition to an increased median intensity of fluorescence (MFI), suggesting that Nod2−/− BMDMs are susceptible to invasion and parasite replication, if compared to WT cells." (PMID 27377650, 2016). "Interestingly, we observed increased bacterial loads in lungs of Nod2-/- mice compared to Wt mice after 24 hours of infection (P<0.05)." (PMID 26673231, 2015). "Interestingly, when we used an unencapsulated pneumococcal strain we found Nod2-/- mice to have increased pulmonary bacterial loads 24 hours after infection." (PMID 26673231, 2015). "Similarly at 24 and 48 hours post-infection Nod2-/- displayed increased levels of MIP-2 in their lungs compared to Wt mice (P<0.01 and P<0.05)." (PMID 26673231, 2015). "NOD-2 polymorphism did not affect the incidence of infection (28.6% vs. 30.3%) or incidence of dialysis (33.2% vs. 30.3%)." (PMID 24393249, 2014). "Thus, while conserved bacterial peptidoglycan fragments are initially recognized by receptors NOD1 and NOD2, the perturbations inflicted over the course of infection can activate NLRP3." (PMID 25254654, 2014). "Moreover, we have shown that Legionella pneumophila, an intracellular bacterium, recruits neutrophils to the site of infection in a Nod1- and Nod2-dependent manner." (PMID 25084278, 2014). "Moreover, NOD2 activates the autophagy process, thereby confining intracellular bacteria within intracellular autophagosomes and subsequently restricting the infection." (PMID 23675299, 2013). "Under most pathological conditions of infection and chronic inflammation it is likely that both NOD2 and multiple TLRs will be activated, a situation that often results in the synergistic stimulation of inflammatory cytokine release by macrophages and other responsive cells." (PMID 23936340, 2013). "Nod2 is upregulated in mouse microglia and individuals with mutated Nod2 were not able to mount an efficient cytokine response after infection with B. burgdorferi." (PMID 24155744, 2013). "Considering that polymicrobial infection and the septic microenvironment appear to differ from those in monomicrobial infections, it is conceivable that NOD2 plays diverse roles in innate immune responses against bacteria, depending on the in vivo microenvironment." (PMID 23675299, 2013). "In a different study, NOD1 and NOD2 had redundant roles in the protection against C. rodentium infection and mediated IL-6-dependent IL-17 production in the cecum at early time point (1–4 days after infection)." (PMID 24381573, 2013). "While NOD2 expression is more restricted, both NODs are expressed in macrophages, dendritic cells, Paneth cells, and intestinal epithelial cells, making them highly suited to sense infections throughout the intestinal tract." (PMID 24381573, 2013). "Using this in vitro infection, neutrophils from mice deficient in TLR2, NOD2 or FPR1 produced significantly less IL-1β protein (40, 43 and 37 percent decrease, respectively) in response to S. aureus, suggesting that activation of TLR2, NOD2 and FPR1 promoted neutrophil production of IL-1β." (PMID 23209417, 2012). "Interestingly, in addition to the detection of bacteria and protozoa, NOD2 has an important role in virus recognition during experimental infection." (PMID 23162548, 2012). "The peptidoglycan fragments from cytoplasm-dwelling bacteria could, therefore, be available for recognition by NOD2 and initiate Nod-dependent cellular responses, making this gene a potential marker for this pathogen infection." (PMID 23046560, 2012). "Consistent with published findings, IFN-β tended to be reduced in the lungs of infected Nod2-/- mice as compared to WT animals during the early phase of infection and Nod2-/- alveolar macrophages produced significantly less IFN-β than WT cells in response to IAV." (PMID 22590599, 2012).
infection (continued). "In this model, Nod2 is a positive regulator of inflammation during the early stages of infection." (PMID 21387014, 2011). "NOD2 is a susceptibility gene for IBD; the NOD2 protein can activate the immune system by triggering NF-κB and can negatively regulate the Toll-like receptor-mediated T-helper type 1 response, thereby increasing susceptibility to infection." (PMID 21977313, 2011). "As suggested by previous transcriptional profiling experiments, we confirmed that Myd88−/−and Rip2−/−macrophages, which are defective in TLR and Nod1/Nod2 signaling, respectively, strongly upregulated Il23a and Gem following infection with wildtype L. pneumophila." (PMID 21390206, 2011). "One possible unifying explanation is that Nod2 may serve different functions in acute versus chronic infections or in infections with a single agent versus conditions where multiple factors, genetic and microbial, are present." (PMID 21387014, 2011). "It is tempting to hypothesize that the differences seen in the role of Nod2 signaling in the inflammatory response to different infections may be related to the “chronicity” of the infection." (PMID 21387014, 2011). "In agreement with the in vitro data, both Nod1−/− and Nod2−/− mice displayed delayed pulmonary bacterial clearance compared to WT controls, as reflected by significantly higher bacterial counts in Nod1−/− and Nod2−/− mice at 5 days post-infection." (PMID 19360122, 2009). "For example, absence of NOD2 in transgenic mice results in increased susceptibility to infection with intracellular pathogens, such as Mycobacterium tuberculosis." (PMID 19709415, 2009). "Interestingly, we observed a strong induction of NOD2 mRNA in C. jejuni infected CMT-93 cells suggesting a potential role for this innate sensor in controlling infection." (PMID 19841748, 2009). "Additionally, when macrophages are tolerized by LPS, the role of NOD1 and NOD2 in cytosolic surveillance becomes more critical during infection." (PMID 18769721, 2008). "Interestingly, it is to note that the slope of the survival curves was similar in both Nod2+/+ and Nod2−/− mice suggesting that, even if delayed, the mechanisms of death (usually due to a generalised infection) should be the same in both mouse strains." (PMID 18648508, 2008). "We thus concluded that Nod2 mediates the susceptibility to infection with Y. pseudotuberculosis via the oral but not the via the intra-peritoneal route." (PMID 18648508, 2008). "To investigate the impact of GIV on NOD2-dependent microbial clearance, we performed gentamicin protection assays in THP1-derived macrophages transfected with either NOD2-WT or the 1007fs variant, followed by infection with adherent-invasive E. coli (AIEC-LF82)." (PMID 40766554, 2025). "Therefore, modulating the activity of NOD1 and NOD2 may potentiate immune response against infections or mitigate detrimental hyperinflammation in certain infectious diseases." (PMID 39329913, 2024). "In a subsequent M. abscessus study of the same model, Nod2-KO in C57BL/6 mice resulted in defective NO production and bacterial control in the lung, both of which could be rescued with recombinant IFN-β, suggesting a NOD2-IFN-β-NO pathway of M. abscessus control early in infection." (PMID 37262021, 2023). "However, less is known about the mechanism of recognition of parasitic infection: whether NOD1 and/or NOD2 directly recognize PAMPs from the parasites, or if the infection is recognized indirectly." (PMID 37006312, 2023). "Furthermore, infection of human fetal brain cells with Zika virus induces NOD2 expression." (PMID 36146565, 2022). "Thus, despite previous reports of impaired immunity in Nod2-KO mice infected with Mtb, mostly gathered within two months post-infection, our data show that any impairment in early cell recruitment tends to recover by 6 weeks post-infection." (PMID 35418999, 2022).
infection (continued). "Altogether, these results indicate that treatment with CL429, a TLR2 and NOD2 agonist, leads to increased production of cytokines and antibacterial mediators ex vivo, in the peritoneal cavity, the bone marrow and the spleen, which are remote from the site of infection." (PMID 31107928, 2019). "However, at 24 h post-infection, the bacterial loads were comparable in Nod2−/− and wild type mice." (PMID 29234083, 2017). "To gain insight into the mechanism of Nod2-mediated early A. baumannii protection, we next measured the lung inflammatory response to determine if the enhanced bacterial load seen in Nod2−/− mice at 4 h post-infection is due to impaired production of cytokines/chemokines." (PMID 29234083, 2017). "In case of Nod2 deficiency, YopJ is no more able to activate the Nod2-dependant Caspase-1 signaling pathway, limiting the ileal inflammation at the beginning of enteral infection." (PMID 28253332, 2017). "We conclude that Nod2 signaling is required for the fine-tuned innate and adaptive local (i.e., intestinal) and systemic immune responses upon C. jejuni infection of secondary abiotic IL-10−/− mice, but does not limit pathogenic infection." (PMID 28752081, 2017). "Because an increased number of L3 larvae had already reached the site of infection in NOD2−/− mice 5 dpi, we hypothesized that the NOD2 dependent mechanism causing the increased worm burden in NOD2−/− mice must occur within the first few days (<5) of infection." (PMID 28004792, 2016). "In this context, the remaining levels of produced chemokines and recruited neutrophils in MyD88-deficient mice could result in the activation of Nod1 and Nod2, which was not enough to control the infection and resolve the septic episode." (PMID 25084278, 2014). "However, NOD1, NOD2, and Rip2 knockout mice were no more susceptible to infection with virulent B. abortus than wild-type mice." (PMID 22203860, 2012). "NOD2 can detect peptidoglycan fragments of mycobacteria, such as MDP, initiating an immune response, particularly in the context of infection and vaccination with BCG." (PMID 40732729, 2025). "NOD2 belongs to the Nod-like receptor (NLR) family of innate immune proteins that play fundamental and pleiotropic roles in host defense against infection and in the control of inflammation." (PMID 40761791, 2025). "SEAP was detected in the supernatants of infected cells at elevated levels at 24 and 48 hours post infection (hpi) for NOD1, however, NOD2 signaling appeared to be delayed as SEAP was only present at appreciable levels in cell supernatants at 48 hpi." (PMID 40502116, 2025). "Infection with the foot-and-mouth disease virus (FMDV) induced transcription of NOD2 while lowering its protein abundance." (PMID 39329913, 2024). "In P. leopardus, TLR5, NOD2, and NLRP3 were all notably induced in the spleen and liver from 6 to 12 h or 24 h post-infection, and the predicted protein structures of three genes were similarly to those of mammals or other fishes." (PMID 39450165, 2024). "In conclusion, the receptor NOD2 is upregulated and activated by an active viral replication in macrophages derived from the THP-1 cell line at early stages of the infection with DENV-2." (PMID 38668261, 2024). "When Rv1096 was ectopically expressed in M. smegmatis, NOD2- and TLR-dependent reduced inflammatory responses plus prolonged bacterial persistence were observed during cellular and C57BL/6 mouse infections." (PMID 37262021, 2023). "We found that NOD2 KO cells had higher paracellular permeability and low resistance to flow-through bacteria on apical side compared to WT cells after 8 h of AIEC-LF82 infection." (PMID 36694274, 2023). "With murine macrophages (peritoneal and BMDMs), the release of IL-1β upon infection with Mtb, BCG and M. abscessus, and Il1b transcription with Mip was NOD2 dependent." (PMID 37262021, 2023).